MCM5 (minichromosome maintenance complex component 5)
Diseases named in the same sentence as MCM5 in open-access papers (continued):
Sharing a sentence is not in itself a finding about the gene and the disease.
renal cell carcinoma (5 papers, 2020 to 2023). "On the other hand, MCM5 was also manifested as a regulator in renal cell carcinoma development which was related with poor prognosis of patients." (PMID 33828075, 2021). "Knockdown of MCM5 can inhibit the proliferation of renal cell carcinoma." (PMID 34993142, 2021). "Gong and his colleagues revealed that ectopic expression of MCM5 had a close correlation with malignancy and poor prognosis, which might be a potential prognostic marker in renal cell carcinoma." (PMID 32964028, 2020). "Additionally, MCM5 was highly expressed in renal cell carcinoma (RCC) tissues and the ablation of MCM5 inhibited RCC cell line proliferation and repressed tumor growth." (PMID 36465369, 2022).
gastric cancer (4 papers, 2020 to 2023). A primary or metastatic malignant neoplasm involving the stomach. "E2F1 may be crucial in the development of gastric cancer by influencing the cell cycle pathway and modulating its target gene MCM3, which may interact with MCM4, MCM5, and MCM7." (PMID 37594635, 2023). "Meanwhile, there have been several articles reveal that MCM2 and MCM5 may serve as prognostic indicators of patients with gastric cancer, but there is no such article on MCM8." (PMID 33155430, 2020). "However, there have been several articles reveal that MCM2 and MCM5 may serve as prognostic indicators of patients with gastric cancer, but there is no such article on MCM8." (PMID 33155430, 2020).
prostate carcinoma (4 papers, 2010 to 2020). A carcinoma that arises from epithelial cells of the prostate gland. "The MCM5 test has previously been shown to have utility in bladder and prostate cancer and has been shown to have signal in cervical intraepithelial neoplasia and Barrets oesophagus." (PMID 33059604, 2020). "It has been previously shown that MCM5 is overexpressed in prostate cancer and that raised MCM5 protein levels are an independent predictor of survival on multivariate analysis in patients treated with radical surgery." (PMID 23717685, 2013). "With respect to prostate cancer, it has been shown that Mcm5 is overexpressed in prostate tissue and serves as an independent predictor of survival in patients undergoing radical prostatectomy, androgen deprivation therapy or radiotherapy." (PMID 22641253, 2012). "In this study we have identified Mcm5 as a potentially important biomarker for prostate cancer detection." (PMID 20648010, 2010). "Urinary Mcm5 detection seems to be a simple, accurate and noninvasive method for identifying patients with prostate cancer." (PMID 20648010, 2010). "MCM5(mini chromosome maintenance 5) is a DNA licensing factor involved in cell proliferation, and has been previously established as an excellent biomarker in a number of malignancies, including cervical, bladder and prostate cancer." (PMID 33059604, 2020). "While Mcm5’s role in prostate cancer detection and diagnosis is still currently being investigated, its usefulness on the development of a panel of biomarkers could be vital for the early detection of prostate cancer in the near future." (PMID 22641253, 2012). "We previously observed that Mcm5 is overexpressed in prostate cancer and that raised Mcm5 protein levels are an independent predictor of survival on multivariate analysis in patients treated with radical surgery or androgen deprivation therapy and radiotherapy." (PMID 20648010, 2010). "Taken together, these studies raise the possibility that detection of elevated levels of Mcm5 may allow identification of prostate cancer patients with clinically significant tumours." (PMID 20648010, 2010). "In this study we investigate Mcm5 as a urinary biomarker for prostate cancer detection." (PMID 20648010, 2010). "Principally, we have shown that Mcm5 levels are elevated in the urine cell sediments of prostate cancer patients when compared with patients without malignancy." (PMID 20648010, 2010). "Although this pilot study has identified Mcm5 as a new biomarker for prostate cancer detection, it is not yet clear whether the test will be able to specifically identify clinically significant cancers." (PMID 20648010, 2010). "Subsequent pilot studies have proposed the utility of MCM5 as a potential new biomarker for prostate cancer detection, but it is not yet clear whether the test will be able to specifically identify clinically significant cancers and this needs to be further investigated." (PMID 23717685, 2013).
acute myeloid leukemia (3 papers, 2021 to 2024). Acute myeloid leukemia (AML) is a group of neoplasms arising from precursor cells committed to the myeloid cell-line differentiation. "Conversely, we also observed that YTHDC1 modulates the expression of MCM2, MCM4, and MCM5 in acute myeloid leukemia (AML) cells by controlling their mRNA stability." (PMID 39414764, 2024).
cervical adenocarcinoma (3 papers, 2021 to 2024). An adenocarcinoma arising from the cervical epithelium. "The MCM5 gene is associated with malignant status and poor prognosis in cervical adenocarcinoma patients, modulates cervical adenocarcinoma cells proliferation, inhibits the cell cycle and promotes colorectal cancer cells in vitro." (PMID 38773180, 2024). "For example, the high MCM5 expression is associated with the malignant state and a poor prognosis in cervical adenocarcinoma patients and regulates the proliferation of cervical adenocarcinoma cells." (PMID 34475953, 2021). "MCM5 is correlated with malignant status and unfavorable prognosis in cervical adenocarcinoma sufferers, and regulates the proliferation of cervical adenocarcinoma cells." (PMID 36479666, 2023).
glioma (3 papers, 2021 to 2025). A benign or malignant brain and spinal cord tumor that arises from glial cells (astrocytes, oligodendrocytes, ependymal cells). "MCM2 and MCM5 are two members of the Minichromosome Maintenance (MCM) family; the entire family of MCMs is promising in glioma prognosis and diagnosis." (PMID 40507925, 2025). "Furthermore, MCM5, MCM8, and MCM10 CNV affected the prognosis of glioma patients." (PMID 36465369, 2022). "Furthermore, MCM5, MCM8, and MCM10 CNV affect the prognosis of glioma patients." (PMID 36465369, 2022).
lung adenocarcinoma (3 papers, 2015 to 2022). A carcinoma that arises from the lung and is characterized by the presence of malignant glandular epithelial cells. "Kaplan–Meier Plotter pan-cancer RNA sequencing was used to estimate the correlation between the MCM5 expression and OS in different immune cell subgroups in patients with lung adenocarcinoma (LUAD)." (PMID 35360518, 2022).
oesophageal cancer (3 papers, 2004 to 2017). "The median level of expression of Mcm5 in malignant bile samples was lower than that we detected in urine and oesophageal aspirates obtained from patients with bladder and oesophageal cancer respectively." (PMID 18414413, 2008). "We have previously shown that the Mcm5 immunofluorometric test is an accurate test for bladder, prostate and oesophageal cancer, and here we show its utility for the diagnosis of pancreatic and biliary tract cancer." (PMID 18414413, 2008). "The expression of MCM5 in malignant biliary brush samples was equivalent to bile aspirates, but lower than that detected in urine and oesophageal aspirates obtained from patients with bladder and oesophageal cancer." (PMID 28081547, 2017). "The elevated levels of the Mcm5 DNA replication licensing protein found in gastric aspirates from patients with oesophageal cancer is consistent with our previous immunohistochemical findings demonstrating aberrant expression of Mcm2 and Mcm5 proteins in dysplastic and malignant oesophageal lesions." (PMID 15266314, 2004). "Elevated levels of Mcm5 in gastric aspirates are highly predictive of oesophageal cancer." (PMID 15266314, 2004). "In this study, we investigated whether minichromosome maintenance protein 5 (Mcm5) can be used to detect oesophageal cancer cells in gastric aspirates." (PMID 15266314, 2004).
oral squamous cell carcinoma (3 papers, 2019 to 2023). "For instance, increased level of MCM5 is remarkably correlated with the positive progression and unfavorable prognosis of oral squamous cell carcinoma, and MCM5 can be utilized as a marker for the early diagnosis of oral squamous cell carcinoma." (PMID 36479666, 2023).
thyroid cancer (3 papers, 2021 to 2023). "MCM5 in thyroid cancer cells was also reported as a target of BET inhibitors." (PMID 36479666, 2023). "Down-regulation of MCM5 by JQ1 BET inhibitor was already identified in thyroid cancer cells." (PMID 36230614, 2022).
cholangitis (2 papers, 2008 to 2017). An acute or chronic inflammatory process affecting the biliary tract. "Benign strictures from bile duct stones, with or without cholangitis did express low levels of MCM5 but median levels were below the detection limit of the assay, reflecting low shedding of any reactive MCM5-positive cells." (PMID 28081547, 2017).
colon cancer (2 papers, 2014 to 2022). "To further verify protein expression, we collected paired colon tumors and NATs and obtained that two of 42-tumor-associated RLBPs, MCM3, and MCM5, exhibited very high expression in tumors compared to the NATs." (PMID 36428700, 2022). "To conclude, we identified two distinct qPCR gene expression profiles correlating with response (low expression of ALDH6A1 + TFF2 + MCM5) and with PFS (KLF12-high + TFF2-low) in advanced colon cancer patients managed with bevacizumab and chemotherapy." (PMID 24555920, 2014).
esophageal cancer (2 papers, 2019 to 2022). A primary or metastatic malignant neoplasm involving the esophagus. "The automatic immunofluorescence detection of Mcm-5 in urine or gastric aspirates is superior in detecting genito-urinary tract cancer and esophageal cancer." (PMID 36010914, 2022).
liver cancer (2 papers, 2019 to 2025). An epithelial or non-epithelial malignant neoplasm that arises from the liver. "In the MCM family, abnormal expression of MCM2, MCM3, MCM4, MCM5, and MCM7 also results in reducing prognosis in liver cancer patients according to the HCCDB database." (PMID 32082966, 2019).
lymph node metastasis (2 papers, 2021). "Higher MCM5 level is significantly related to tumor size, histopathological stage, lymph node metastasis and prognosis." (PMID 34993142, 2021). "Also, MCM5 is closely related to clinical stage, lymph node metastasis, distant metastasis, and histological grade." (PMID 34530829, 2021).
Meier-Gorlin syndrome (2 papers, 2017 to 2022). "Recently, MCM5 was also identified as likely causative in the human Meier-Gorlin Syndrome, a rare developmental disorder characterized by growth retardation." (PMID 35737938, 2022). "A form of dwarfism known as Meier-Gorlin syndrome (MGS) is caused by recessive mutations in one of six different genes (ORC1, ORC4, ORC6, CDC6, CDT1, and MCM5)." (PMID 29036220, 2017).
neuroblastoma (2 papers, 2014 to 2015). Neuroblastoma (NB) is the most common solid, extracranial childhood tumor.
ovarian adenocarcinoma (2 papers, 2007 to 2018). An adenocarcinoma that arises from the ovary. "Similarly, the labeling indices of MCM2 and MCM5 proteins of ovarian adenocarcinomas were associated with adverse patient outcomes in univariate and multivariate analyses." (PMID 29963273, 2018). "In conclusion, MCM-2 and MCM-5 proteins appear to be promising as prognostic markers in patients with ovarian adenocarcinomas." (PMID 17940502, 2007). "A main scope of our study was to investigate for the first time the prognostic relevance of MCM-2 and MCM-5 expression in ovarian adenocarcinomas." (PMID 17940502, 2007). "Therefore, MCM2 and MCM5 proteins are promising prognostic markers in patients with ovarian adenocarcinoma." (PMID 29963273, 2018). "In ovarian adenocarcinomas, MCM-2 and MCM-5 expression increased with increasing tumour grade, advancing stage and the presence of bulk residual disease." (PMID 17940502, 2007). "In conclusion, in the present study, we have investigated for the first time MCM-2 and MCM-5 expression in LMP tumours and ovarian adenocarcinomas in relation with clinicopathologic parameters, cell cycle modulators and patients’ survival." (PMID 17940502, 2007). "Minichromosome maintenance protein-2 and MCM-5 proteins demonstrated increased expression in ovarian adenocarcinomas as opposed to LMP tumours." (PMID 17940502, 2007).
ovarian neoplasm (2 papers, 2007 to 2020). A benign, borderline, or malignant neoplasm involving the ovary. "In the present study, we have clearly demonstrated the nuclear localisation of MCM-2 and MCM-5 proteins in ovarian neoplasms." (PMID 17940502, 2007).
pancreatic cancer (2 papers, 2021). "MCM genes including MCM2, MCM5 and MCM6 were upregulated in pancreatic cancer and show strong positive coexistence with each other." (PMID 33507917, 2021).
squamous cell carcinoma (2 papers, 2022 to 2023). A carcinoma arising from squamous epithelial cells. "Typically, lncRNAs act via target molecules, such as lncPOP1-1, that promotes cisplatin resistance in squamous cell carcinoma, which occurs in the neck, by interacting with MCM5." (PMID 36717926, 2023).
anemia (1 paper, 2019). A reduction in the number of red blood cells, the amount of hemoglobin, and/or the volume of packed red blood cells. "We examined global transcriptome alterations following depletion of DNA replication checkpoint genes (Atr, Mcm4, Mcm5, and Mcm6), the Fanconi anemia gene (Fanca), mRNA processing genes (Snrpal and Snrpd3), and CMT genes (Sh3tc2 and Cmt4b2)." (PMID 31390555, 2019).
Barrett's oesophagus (1 paper, 2009). "This has also been observed in studies of Mcm2 and Ki67 in Barrett's oesophagus and in neoplastic oesophagus using Mcm5." (PMID 19293805, 2009).
benign prostatic hyperplasia (1 paper, 2010). A non-cancerous nodular enlargement of the prostate gland. "Notably, Mcm5 was undetectable in 70 patients with benign prostatic hyperplasia." (PMID 20648010, 2010).
brain tumors (1 paper, 2019). "MCM5 is a proliferation marker in brain tumors, and expression of DRAM1 is related to neuronal autophagy." (PMID 31428131, 2019).
cervical squamous intraepithelial lesions (1 paper, 2016). "The diagnostic value of MCM proteins was first verified when antibodies against MCM5 andKi-67 were compared in cervical squamous intraepithelial lesions." (PMID 27780919, 2016).
cognitive deficits (1 paper, 2022). "However, the MCM5 mutant patient identified thus far (p.T466I) did not display apparent cognitive deficits or microcephaly." (PMID 35737938, 2022).
colon adenoma (1 paper, 2020). An adenoma that arises from the colon. "Among them, CRC overexpression of minichromosome maintenance complex component 5 (MCM5) was validated by immunohistochemical staining in a TMA containing 82 colon adenomas and 82 CRCs." (PMID 32878319, 2020).
dyspepsia (1 paper, 2004). An uncomfortable, often painful feeling in the stomach, resulting from impaired digestion. "Two monoclonal antibodies raised against His-tagged human Mcm5 were used in a time-resolved immunofluorometric assay to measure Mcm5 levels in cells isolated from gastric aspirates of 40 patients undergoing gastroscopy for suspected or known oesophageal carcinoma or symptoms of dyspepsia." (PMID 15266314, 2004).
endometrial tumours (1 paper, 2020). "MCM5 is a novel sensitive and specific biomarker for the detection of ovarian and endometrial tumours in urine samples, which is likely to have clinical utility as a diagnostic aid." (PMID 33059604, 2020).
gastrointestinal carcinomas (1 paper, 2014). "Data from clinical and preclinical models of skin, esophageal, bladder and gastrointestinal carcinomas further confirm the proliferative, migratory and cell cycle activating properties of the MCM5 protein." (PMID 24555920, 2014).
head and neck cancer (1 paper, 2025). A primary or metastatic malignant neoplasm affecting the head and neck. "In stomach, prostate, liver, and HPV− head and neck cancers, most genes were correlated except MCM5 or MAP17." (PMID 40548474, 2025).
Hyperglycemia (1 paper, 2025). An increased concentration of glucose in the blood. "Mechanistically, hyperglycemia-activated FIBCD1 promoted MCM5 expression to induce S-phase cell cycle arrest by upregulating histone H3K27ac levels in MCM5 promoter via the PDH-acetyl-CoA axis." (PMID 40695783, 2025). "Importantly, the rescue effects of si-MCM5 on FIBCD1-mediated cell cycle dysregulation were stronger under hyperglycemia conditions than that of physiological culture conditions." (PMID 40695783, 2025). "In this study, we found that hyperglycemia upregulated the expression of FIBCD1, which activated MCM5 expression to affect cell cycle and proliferation via the PDH-acetyl-CoA axis." (PMID 40695783, 2025). "Collectively, these results suggest that hyperglycemia-induced FIBCD1 activates production of PDH, which catalyzes the generation of acetyl-CoA, thus increasing H3K27ac level and promoting MCM5 expression." (PMID 40695783, 2025).
ischemic heart disease (1 paper, 2022). "Among the genes, 1-hop and 2-hop neighbors in the underlying network, were chromatin licensing and DNA replication factor 1 (CDT1), minichromosome maintenance complex component 5 (MCM5), and cAMP-responsive element-binding protein 1 (CREB1), which have been linked to ischemic heart disease before." (PMID 35903362, 2022).
large-cell lung carcinoma (1 paper, 2021). "Furthermore, MCM5 showed a high expression level with a fold change of 4.628 in LUSC samples in Bhattacharjee’s dataset, while MCM7 exhibiting an increased mRNA level in large-cell lung carcinoma with a fold change of 4.547 in Hou’s dataset." (PMID 33936158, 2021).
malaria (1 paper, 2012). Malaria is a serious and sometimes fatal disease caused by a parasite that commonly infects a certain type of mosquito which feeds on humans. "Moreover, the two genes immediately flanking the HMOX1 gene (TOM1 33 kb 5′ and MCM5 6 kb 3′ of HMOX1) are not obvious candidates for malaria susceptibility." (PMID 22438807, 2012).
malignant fibrous histiocytoma (1 paper, 2021). "Using Detwiller Sarcoma’s datasets, MCM5 was also found to be overexpressed in malignant fibrous histiocytoma (fold change = 4.703) compared with normal samples." (PMID 34239894, 2021).
mastitis (1 paper, 2022). Inflammation of breast tissue during lactation or postpartum due to an obstructed duct or infection. "In this study, the increased gene expression of ORC1, ORC2, ORC4, MCM3, MCM5, and MCM6 in the neutrophils of cows with high SCCs indicated that the cell cycle may be activated in neutrophils in high mastitis risk cows during the transition period." (PMID 35572521, 2022).